CD93 (CD93 molecule)
Diseases named in the same sentence as CD93 in open-access papers (continued):
Sharing a sentence is not in itself a finding about the gene and the disease.
infection (15 papers, 2014 to 2025). The state of being infected such as from the introduction of a foreign agent such as serum, vaccine, antigenic substance or organism. "Six weeks into infection, mice showed a nearly complete ablation of the CD93+ early linage B cells in the bone marrow, while these cells should under homeostatic conditions be present in order to replenish the periphery." (PMID 34762705, 2021). "T1 B cells from both WT and BAFFR-/- mice either before or after infection expressed similarly high levels of CD93, indicating that they retained their immature phenotype." (PMID 29176765, 2017). "Western blotting analyses revealed that in CD93-silenced cells each infection restored CD93 at the same expression levels as observed in cells expressing an unrelated shRNA, whereas endogenous CD93 was completely knocked down." (PMID 26848865, 2016). "A study of gammaherpesvirus infection in mice has demonstrated that the majority of normal B cells were activated in the course infection with downregulation of CD93." (PMID 27529750, 2016). "Notably, FcεR1γ-deficient ILC3s showed a significant decrease in the expression of infection-induced immune activation genes, such as Fcgr3, Ccr7, Il22, Il17a and Cd93." (PMID 39013884, 2024). "Whether chronic schistosomiasis deleteriously solicits the bone marrow hematopoietic machinery as the infection progresses and as such interferes with the maintenance of essential survival cues within the bone marrow for plasma cells such as CD93 expression is to be addressed." (PMID 35157732, 2022). "CD93 and FCGR2A (encoding CD32/FcγRIIa) which mediate the enhancement of phagocytosis in monocytes and macrophages were upregulated during infection on CD16+ monocytes and cDCs, but not CD14+ monocytes." (PMID 37968278, 2023). "HUVEC infected with lentiviruses expressing either CD93 shRNA showed reduced CD93 protein levels while no CD93 reduction was revealed upon infection with a lentivirus expressing an unrelated shRNA." (PMID 24809468, 2014). "This coincides with ablation of the early B lineage CD93+ bone marrow compartment, resulting in the absence of mature B cells replenishment in the periphery and the long-term inability of the host to control the infection." (PMID 34762705, 2021).
cardiovascular disease (7 papers, 2012 to 2025). "CD93 was identified among the top 10 biological pathways and regulatory genes linked to cardiovascular disease and type 2 diabetes." (PMID 40943530, 2025). "Whether the low plasma levels of CD93 in patients is a significant level for both risk for cardiovascular diseases and CRC, or whether it reflects similar physiological and pathological mechanisms in the regulation of CD93 need to be further investigated." (PMID 26008729, 2015). "However, CD93 is dominantly expressed in the endothelium, and soluble CD93 fragments were detected in the circulation of patients with cardiovascular disease." (PMID 23272129, 2012). "Finally, CD93 plays a role in cardiovascular disease development and progression." (PMID 37443812, 2023).
immune diseases (2 papers, 2020 to 2022). "CD93 has been shown critical roles in inflammatory and immune diseases." (PMID 31941986, 2020).
psychiatric diseases (2 papers, 2022 to 2025). "Furthermore, CD93 knockout mice exhibited autism-like behaviors, providing new insights into the pathogenesis of psychiatric diseases." (PMID 40943530, 2025). "Elevated levels of TNFR1/2, CD93 and suPAR levels may reflect a unique pattern of inflammation that is particularly relevant to a subgroup of individuals with psychiatric disorders." (PMID 36085284, 2022).
infectious disease (1 paper, 2017). A disorder directly resulting from the presence and activity of a microbial, viral, or parasitic agent in humans. "In contrast, the serum levels of TIMP1, TKT, and CD93 were significantly higher in patients with active AAV than in those with infectious diseases." (PMID 28962592, 2017). "In addition, TKT seems to be a better biomarker than CD93 for reflecting renal involvement because the level of TKT was less elevated than that of CD93 in patients with infectious diseases." (PMID 28962592, 2017).
CD93 also shares sentences with these, for which no sentence is quoted: colon cancer (3 papers); diabetes (3); myocardial infarction (3); viral infection (3); cervical squamous cell carcinoma (2); colon adenocarcinoma (2); COVID-19 (2); Diabetic Nephropathy (2); fibrosarcoma (2); Lung squamous cell carcinoma (2); malignant glioma (2); Pan (2); uterine corpus endometrial carcinoma (2); acute leukemia (1); acute myocardial infarction (1); adrenocortical carcinoma (1); AIDS (1); aleutian mink disease (1); alveolar proteinosis (1); astrocytoma (1); bacterial infections (1); bladder cancer (1); bladder urothelial carcinoma (1); Cerebral ischemia (1); cerebrovascular diseases (1); chronic obstructive pulmonary disease (1); clear cell renal cell carcinoma (1); dyslipidemia (1); endocervical adenocarcinoma (1); endometrial cancer (1).
A further 18 diseases each share a sentence with CD93 in 1 paper.